BRAF (B-Raf proto-oncogene, serine/threonine kinase)
Diseases named in the same sentence as BRAF in open-access papers (continued):
Sharing a sentence is not in itself a finding about the gene and the disease.
melanoma (continued). "For instance, in BRAF-mutant melanoma, inhibition of the MAPK pathway induces tumor cells to activate alternative survival pathways via epigenetic or non-genetic mechanisms, leading to treatment escape." (PMID 41256326, 2025). "Resistance to BRAF inhibition (BRAFi) is a significant clinical obstacle, as certain melanoma cells can downregulate key regulators of melanocyte differentiation, such as MITF, and upregulate RTKs like AXL and EGFR." (PMID 40386826, 2025). "With the advent of modern targeted immunotherapies, adjuvant therapy with immunotherapy and BRAF inhibitors has become the standard of post-surgical care for resection of malignant melanoma." (PMID 40236344, 2025). "Following the completion of treatment, the patient did not have any recurrent melanoma until October 2023, when they developed a peri-gastric mass that was biopsied and confirmed the diagnosis of BRAF D594N mutant melanoma." (PMID 41333460, 2025). "The FDA-approved BRAF inhibitors dabrafenib, vemurafenib, encorafenib, and binimetinib are used in the treatment of patients with BRAF-mutant melanoma by selectively targeting BRAF kinase and interfering MAPK signalling pathway." (PMID 40793752, 2025). "Researchers are developing or seeking drugs that can specifically induce apoptosis in melanoma cells and exploring their combined use with BRAF inhibitors, MEK inhibitors, or immunotherapy." (PMID 40331942, 2025). "New strategies target ERK1/2 directly; the ERK inhibitor ulixertinib (BVD-523) has shown promise in trials and received expanded access for BRAF-mutant melanoma." (PMID 40363930, 2025). "Activation of mutant RAS oncogenes is common in human cancers, and about 15%–20% of melanoma patients contain NRAS mutations, which are oncoproteins that activate BRAF signaling pathways." (PMID 41355975, 2025). "Conversely, we observed fewer BRAF-mutated MMs in HCMV positive patients than expected, suggesting a preventive role against melanoma with this mutation." (PMID 41194666, 2025). "Sullivan and colleagues, in a clinical Phase I study performed on advanced solid tumor, including iCCA, demonstrated that Ulixertinib can be considered a potential monotherapy drug in tumors with BRAF-mutant melanoma." (PMID 40723336, 2025). "Encorafenib induced autophagy and senescence in BRAFV600E melanoma cells, while the combination of encorafenib with an autophagy inhibitor showed increased antiproliferative activity against BRAF-mutant cells." (PMID 39935431, 2025). "We focused on the literature published on BRAF V600E in melanoma, papillary thyroid carcinoma, and colorectal cancer." (PMID 40977811, 2025). "The observed decrease in phosphorylation levels of BRAF, PI3K, AKT1, and mTOR is particularly relevant, as constitutive activation of these pathways has been strongly associated with melanoma growth and resistance to therapy." (PMID 40806647, 2025). "Co-targeting neurotrophin receptors with MAPK pathway members, particularly in combination with BRAF inhibitors, appears a promising approach for treating melanoma brain metastases." (PMID 41394583, 2025). "For metastatic melanoma patients who progress on ICI therapy, BRAF/MEK inhibitors offer an additional follow-up therapy option for patients with BRAF-mutant (BRAFV600E) advanced melanoma." (PMID 40904502, 2025). "Despite significant advances in melanoma treatment, including the development of BRAF/MEK inhibitors and immune checkpoint blockers, therapeutic resistance remains a major obstacle." (PMID 41034991, 2025).
melanoma (continued). "Similary to the results from the multinomial regression, ROC analyses found a different survival impact of the presence of brain metastases between BRAF-mutant and BRAF-wildtype melanoma patients." (PMID 40028330, 2025). "The resistance mechanisms underlying BRAF and MEK inhibitor therapy in melanoma are multifaceted and involve complex molecular pathways that significantly limit the durability of therapeutic responses." (PMID 39897423, 2025). "Senescence in PDX BRAF-mutant MM27 melanoma cells was inhibited by deubiquitinase (DUB) USP7-mediated stabilization of RRM2." (PMID 39935431, 2025). "Targeting YB-1 using RSK inhibitors re-sensitizes vemurafinib-resistant melanoma cells to BRAF inhibitors." (PMID 41516092, 2025). "In our melanoma study, the IC50 for ML in BRAF-mutated A-2058 cells was 11.1 nM, making it the most responsive cell line to the antagonist." (PMID 40004697, 2025). "Alongside direct antiproliferative effects, BRAF inhibition induces changes in melanoma cell differentiation status, with increased expression of melanocyte differentiation antigens and restored pigmentation in some cases." (PMID 41614813, 2025). "Therapeutic strategies aimed at modulating the immune microenvironment, particularly macrophage activity and cytokine production, hold promise for mitigating resistance and improving patient outcomes in melanoma treated with BRAF/MAPK-targeted therapies." (PMID 40872623, 2025). "By inhibiting mutated BRAF, it prevents downstream MEK-ERK activation, reducing tumor cell proliferation and survival in cancers dependent on aberrant BRAF signaling, such as melanoma." (PMID 41368991, 2025). "Silencing of HSP70 led to increased SG formation and sensitized melanoma cells to apoptosis, particularly in response to the BRAF inhibitor Vemurafenib." (PMID 41148289, 2025). "By comparing gene expression in melanoma cell lines that were either sensitive or resistant to the BRAF inhibitor dabrafenib, they observed that miR-181a/b levels were higher in BRAFi-sensitive cells." (PMID 41515546, 2025). "In melanoma, aberrant activation of the BRAF/MEK signaling pathway plays a pivotal role in tumor progression, with mutations in the BRAF kinase being present in approximately 50% of melanomas, leading to the constitutive activation of the MAPK/ERK pathway." (PMID 40243953, 2025). "The identification of BRAF fusions highlights the clinical significance of gene fusions in advanced melanoma." (PMID 40737104, 2025). "While genetic mutations such as BRAF activation and PTEN loss drive early melanoma formation, the mechanisms underlying metastasis remain less characterized." (PMID 41286309, 2025). "As expected, BRAF-driven tumors strongly mapped to the melanoblast and melanophore clusters, supporting recent findings that BRAF-driven melanoma originates from melanoblasts, a melanocyte progenitor population." (PMID 40950146, 2025). "Specifically, there is an urgent demand for new therapies aimed at patients with BRAF wild-type tumors who advance despite immunotherapy and those with BRAF-mutant melanoma who progress on both immunotherapy and BRAF-MEK targeted treatments." (PMID 40282469, 2025). "It has been reported that HHT enhances the sensitivity of A375R to vemurafenib in BRAF-mutant melanoma cells that have become resistant, specifically the A375R cells." (PMID 39790031, 2025). "We selected 16 dermoscopic features and compared the BRAFWT melanoma group with the BRAF-mutant melanoma group according to the dermoscopic images." (PMID 41010758, 2025). "Other drugs, like vemurafenib, dabrafenib, and encorafenib, which are BRAF inhibitors, were approved by the FDA for the treatment of melanoma with the BRAF V600 mutation." (PMID 40564101, 2025). "Here we set out to investigate the impact of GSK3β on the development of BRAF inhibitor (BRAFi) resistance in melanoma." (PMID 40184329, 2025).
melanoma (continued). "BRAF and NRAS oncogenic mutations, as well as environmental factors such as ultraviolet (UV) exposure, have traditionally dominated discussions of melanoma progression." (PMID 40940929, 2025). "In patients with BRAF V600-mutant melanoma, the combination of dabrafenib and trametinib offers a targeted adjuvant approach." (PMID 40984902, 2025). "In fact, clinical activity of combined pan-Hsp90 and BRAF V600E inhibition was found in patients with unresectable BRAF V600E-mutant melanoma." (PMID 40498011, 2025). "For example, in melanoma, the BRAF inhibitor PLX4720 induces ER stress-mediated autophagy via the PERK kinase." (PMID 40278350, 2025). "Therapeutical inhibition of BMP2 activity reduces invasive phenotypes and sensitizes melanomas to BRAF/MEK inhibition." (PMID 41470117, 2025). "A total of 49 patients with BRAF-mutant advanced melanoma treated with BRAFi/MEKi were included in the analysis." (PMID 41294692, 2025). "Recently, the nuclear-localized SIRT7 deacetylase was correlated with acquired drug resistance in BRAF-mutant melanoma through the promotion of mitochondrial biogenesis." (PMID 39935431, 2025). "We established two BRAF inhibitor (BRAFi)-resistant melanoma cell lines using BRAF mutant 451Lu and UACC62." (PMID 40592836, 2025). "In the following analyses, patients were divided into PD‐1 (NIV/PEM) and BRAF + MEK (D + T) cohorts based on their second course of adjuvant melanoma therapy after recurrence during or after the first adjuvant treatment (RFS2)." (PMID 40331873, 2025). "NRAS mutations, particularly NRAS Q61K/R, are a commonly observed acquired resistance mechanism in patients with BRAF-mutant melanoma treated with BRAF+/−MEK inhibitors." (PMID 39859576, 2025). "For example, elevated IL‐6 and CCL2 in BRAF‐inhibitor‐induced TIS models of melanoma correlated with increased infiltration of immunosuppressive macrophages, which dampened anti‐tumor T cell activity." (PMID 40926366, 2025). "The mechanisms of resistance to inhibition of the BRAF signaling pathway have been elucidated by the metabolic plasticity of melanoma and reprogramming from glycolysis to mitochondrial metabolism." (PMID 41515422, 2025). "Early studies have also explored the significant activation of the WNT pathway through the action of FZD7 in BRAF inhibitor-resistant melanoma cells." (PMID 40611274, 2025). "BRAF-mutant melanomas appear more frequently in younger patients, under 40 years old, while BRAFWT melanomas are more commonly diagnosed in older patients." (PMID 41010758, 2025). "In BRAF inhibitor resistance, exosome-derived growth factors and interleukins released by resistant melanoma cells promote the transition of M2 macrophages." (PMID 40058234, 2025). "With this approach, we successfully transdifferentiated BRAF-mutated (A375, HT144, MA1) and NRAS-mutated human melanoma cells (SKMel30, SKMel103) as well as murine Ret melanoma cells derived from Ret transgenic mice." (PMID 40715046, 2025). "NRAS mutant melanoma accounts for approximately 15–20% of melanoma cases and is characterized by a more aggressive clinical course compared to BRAF mutant melanoma." (PMID 40867277, 2025). "For example, reactivation of the MAPK pathway downstream of BRAF via MEK or ERK mutations has been documented in patients progressing on BRAF/MEK inhibitors, underscoring the adaptive plasticity of melanoma cells." (PMID 41302945, 2025). "Research has shown that hypoxia can induce a switch in melanoma cells from a receptor tyrosine kinase-like orphan receptor 1 (ROR1)+ to a more invasive ROR2+ phenotype, which is associated with resistance to BRAF inhibitors." (PMID 40867277, 2025). "In particular, in a phase 2 clinical trial, patients with BRAF V600E-mutant lung cancer were found to benefit clinically from vemurafenib, a BRAF inhibitor authorized for the treatment of BRAF V600E-mutant melanoma." (PMID 40361442, 2025).
melanoma (continued). "The effectiveness of this approach was demonstrated in a phase 3 clinical trial involving patients who had underwent resection of a stage III BRAF V600E or V600K-positive melanoma followed by 12-month adjuvant therapy (dabrafenib + trametinib)." (PMID 40977811, 2025). "In melanoma, immunotherapy and BRAF-targeted therapy have demonstrated reliable positive outcomes; however, their current use is limited to an adjuvant setting or as an alternative for unresectable cancers." (PMID 40723254, 2025). "Accordingly, selective BH3 mimetics synergistically improved TTM efficacy by inducing apoptosis in BRAF-mutant melanoma, both drug-naïve and resistant to BRAF or MEK1/2 inhibitors." (PMID 39970778, 2025). "SC-62-1 potently inhibits and eliminates clonogenic growth of melanoma cells that acquired resistance to BRAF inhibitors." (PMID 40649216, 2025). "While there is evidence supporting its influence on immunotherapy response in melanoma, its impact on BRAF/MEK-targeted therapy remains unexplored." (PMID 40659866, 2025). "Initial studies indicate that pirin expression and its regulatory role on MRTF are significantly elevated in BRAF-mutant melanoma cells, potentially making these subtypes more vulnerable to concurrent targeting of Rho/MRTF and pirin." (PMID 40740997, 2025). "Our study extends this analysis to a larger panel of melanoma cell lines, including non-BRAF mutants." (PMID 40943167, 2025). "The current standard of care for stage III melanoma includes single-agent PD-1 inhibitor therapy for one year following surgical management, or a combination of BRAF/MEK inhibitors for BRAF-mutated patients." (PMID 40161129, 2025). "Osimertinib-resistant NSCLC cells enhance OXPHOS activity, and BRAF inhibitor-resistant melanomas activate PGC-1α-mediated mitochondrial biogenesis, further increasing the cristae density and elevating oxidative capacity." (PMID 40725147, 2025). "Approximately half of patients with advanced melanoma harbor activating BRAF mutations that drive MEK/ERK pathway activation and initially respond to BRAF inhibitors, but most relapse within months due to acquired resistance." (PMID 41155949, 2025). "We find that Rac1-driven melanomas manifest pleiotropic resistance mechanisms including (i) reduced dependence on BRAF/MEK, (ii) activation of alternative MAPK pathways utilizing Jun kinase and p38 MAP kinase, and (iii) a partial reliance on YAP/TAZ signaling." (PMID 41109929, 2025). "Panobinostat restored BRAF inhibitor sensitivity in BRAF-mutant melanoma cells with acquired vemurafenib resistance by suppressing PI3K signaling and c-Myc, which was accompanied by the induction of pro-apoptotic BIM and NOXA." (PMID 39935431, 2025). "Vemurafenib showed unprecedented efficacy in BRAF-mutant melanoma and was approved by the FDA in 2011." (PMID 41473206, 2025). "The current standard of care for patients with mutant BRAF melanoma who have failed immunotherapy is the combined inhibition of BRAF and MEK." (PMID 39922199, 2025). "(2005) showed that acral melanomas often have distinct genetic alterations compared to other melanoma subtypes, including a higher prevalence of KIT mutations (15%–20% of cases) and a lower frequency of BRAF mutations (less than 5%)." (PMID 41164124, 2025). "Complexes 2b and 2c exhibited the most potent activity against melanoma BRAF WT (MeWo) and bladder cancer (T24), with 2c showing the highest selectivity toward these cancer cell lines (selectivity index of ca. 3.0)." (PMID 40244013, 2025). "A study found that alisertib combined with trametinib treatment in BRAF mutant melanoma patient-derived drug resistance models can alter metabolic reprogramming and enhance FAO." (PMID 40514365, 2025). "These primarily encompass BRAF V600E mutations, which we observed also in our cohort and have proven more difficult to target in CRC compared, for example, to melanoma." (PMID 39876058, 2025).
melanoma (continued). "Experience from melanoma brain metastases shows that combining BRAF/MEK inhibitors with PD-1/CTLA-4 checkpoint inhibitors improves intracranial tumor control, and some authors have extrapolated this approach to primary meningeal melanoma." (PMID 41294657, 2025). "Lipid metabolism pathways revealed significant dysregulation in melanoma progression and resistance to BRAF/MEKi." (PMID 41550951, 2025). "This uncovered heterogeneities in tumor morphology, protein profiles, and clinical outcomes in a limited subset of BRAF V600-positive melanomas." (PMID 40075679, 2025). "Here, we showed the utility of a piggyBac transposon activation mutagenesis screen for the efficient identification of genes that are resistant to BRAF inhibition in melanoma." (PMID 39856157, 2025). "Metabolism reprogramming induced by 2DG makes the neuroblastoma RAS viral oncogene homolog (NRAS) mutant melanoma cells sensitive to BRAF inhibitor (BRAFi) sorafenib." (PMID 40617808, 2025). "A375 melanoma cells were transfected with BRAF(V600E)-siRNA and subsequently treated with TRE, HCQ, or their combination." (PMID 41170188, 2025). "Recent evidence has elucidated a pivotal role of ferroptosis in modulating therapeutic resistance in BRAF-mutant melanoma." (PMID 40909289, 2025). "BRAF, particularly the V600E mutant that drives many melanomas, has been targeted by P4B, SJF‐0628, and the newer SJF‐0651, which shows improved selectivity for the mutant form." (PMID 41049269, 2025). "For instance, the BRAF V600E mutation triggers the activation of both IRE1 and ATF6 in melanoma cells." (PMID 40278350, 2025). "Immune checkpoint inhibitors (ICI) have significantly improved melanoma-specific survival (MSS), particularly in patients with tumors with a high tumor mutational burden (TMB) or BRAF mutation." (PMID 40874224, 2025). "Our findings shed new light on the mechanism of cell death induced by disulfiram, supporting its further application in BRAF-mutant melanoma." (PMID 40592836, 2025). "Trichostatin A also suppressed c-Myc in BRAF-mutant SK-MEL-3 melanoma cells; however, this compound predominantly induced mitotic arrest and cytostatic effects, rather than causing cell death." (PMID 39935431, 2025). "Mutations of the BRAF gene and mitogen-activated protein kinase (MAPK) are common causative agents of melanoma." (PMID 41155918, 2025). "One of the most prevalent genetic alterations observed in melanoma is V600E in B-Raf murine sarcoma viral oncogene homolog B (BRAF), which largely contributes to constitutive activation of the RAS/RAF/MEK/ERK signaling pathway, known as the MAPK pathway." (PMID 41227355, 2025). "Significance: Cotargeting the MAPK and the PREX2/RAC1/PI3Kβ pathways has remarkable efficacy and outperforms monotherapy MAPK inhibition in BRAF-mutant melanoma, supporting the potential of this combination therapy for treating metastatic melanoma." (PMID 39636745, 2025). "It is now well established that patients with BRAF-mutant melanoma can benefit from both targeted therapies and immunotherapy." (PMID 40507236, 2025). "The effects of HDACs on cell growth and survival were predominantly studied in BRAFV600E melanoma models, but also other BRAF-altered cancers, such as colon cancer and thyroid cancer, revealed HDAC-dependent mechanisms of cell death." (PMID 39935431, 2025). "Advances in systemic therapy with immune checkpoint inhibitors and BRAF-targeted therapies were also responsible for increasing survival rates in advanced melanoma." (PMID 40941017, 2025). "We performed a prospective, multicentre, 12-month PMS of the safety and effectiveness of encorafenib plus binimetinib for radically unresectable, BRAF-mutant malignant melanoma in Japan." (PMID 39918770, 2025). "Both dabrafenib and trametinib (D + T) and anti-PD(L)1s have been shown to improve recurrence-free survival (RFS) in patients with stage III or resected stage IV BRAF-mutant melanoma." (PMID 40758471, 2025).